LIF (LIF interleukin 6 family cytokine)
Diseases named in the same sentence as LIF in open-access papers (continued):
Sharing a sentence is not in itself a finding about the gene and the disease.
tumor (continued). "While several inflammatory mediators (IL-6, TNF-α, TWEAK, TRAF6, INF-γ, and LIF) have been implicated as drivers of cancer-associated wasting, very little is known about their origin, whether skeletal muscle, immune cell, or tumor-derived." (PMID 32982782, 2020). "However, the underlying mechanism of LIF's promoting effects on tumor progression and metastasis is poorly defined." (PMID 26716902, 2016). "Despite the important role of LIF in tumor metastasis, its underlying mechanism is far from clear." (PMID 26716902, 2016). "Overall, LIF plays an important pathophysiological role in cancer and cardiovascular diseases, and may be considered as a new inflammatory biomarker to monitor the status of tumor progression and underlying cardiovascular damage in NSCLC patients." (PMID 37103052, 2023). "Also, LIF expression has been shown to have correlation with tumor-associated macrophages, and on the other hand, LIF inhibition/neutralization was able to induce tumor infiltration of CD8 + T cells, natural killer cells, and regulatory T cells." (PMID 36809715, 2023). "Finally, PGLYRP3, GAL, ADCYAP1R1 and LIF were selected to construct the Tumor Mutation Burden Immune Prognostic model (TMB-IP) using the following formula: TMB-IP score = (PGLYRP3*0.0988045135949462 + GAL*0.0483710471635067 + ADCYAP1R1*0.123387518699318 − LIF*0.121787959868336)." (PMID 33836680, 2021). "In addition to an altered metabolic phenotype, inflammation has been reported to play a significant role in the progression and treatment response of OAC tumours, whereby elevated levels of pro-inflammatory mediators such as LIF, C3a, C4a and IL-1β have been associated with poor treatment response." (PMID 32694701, 2020). "Leukemia Inhibitory Factor (LIF), a pleiotropic cytokine implicated in tumor progression and metabolic dysregulation, has emerged as a potential regulator of cachexia-related pathways." (PMID 41744798, 2026). "Tumor-bearing mice were treated with two doses of standard of care gemcitabine/nab-paclitaxel, followed by twice-weekly doses of anti-LIF and anti-PD-L1." (PMID 39857986, 2025). "In summary, the combination of chemotherapy, anti-LIF, and anti-PD-L1 not only targets tumor cells but also modulates the broader tumor immune response." (PMID 39857986, 2025). "Bile acids, shown to function as endogenous antagonists of leukemia inhibitory factor (LIF), bind to a heterodimeric receptor during tumor initiation." (PMID 40529304, 2025). "Targeting LIF signaling can reduce TANs, expand antigen-specific T cells, inhibit tumor progression, and reverse the immunosuppressive tumor microenvironment." (PMID 40568576, 2025). "SOX9 KO in both GA0518 and AGS cells led to significantly decreased LIF transcription and secretion; LIF and SOX9 were co‐expressed in tumor cells, and LIF was elevated in malignant ascites but undetectable in plasma and cytology‐negative peritoneal washings." (PMID 41163398, 2025). "We investigated populations of myeloid cells and observed an increase in monocytes and a decrease in granulocytes within the tumor following chemo/anti-LIF/anti-PD-L1." (PMID 39857986, 2025). "Given LIF's established involvement in inflammation and immune regulation, these findings suggest its potential as both a driver of tumor progression and a predictive biomarker for immune‐related adverse events in ICI‐treated patients." (PMID 41163398, 2025). "Our data suggest a potential signature for anti-LIF treatment, characterized by reduced tumor stemness, proliferation, and metabolism-related signaling." (PMID 39857986, 2025).
tumor (continued). "LIF has been shown to promote tumor cell stemness, EMT, growth, and survival, contributing to chemo/radiotherapy resistance in various tumor types, including PDAC." (PMID 39857986, 2025). "The chemo/anti-LIF/anti-PD-L1 treatment decreased mesenchymal tumor cells and augmented the antitumor immune response, primarily driven by CD8 T cells, as depleting these cells diminished the treatment’s effectiveness." (PMID 39857986, 2025). "This chemo/anti-LIF/anti-PD-L1 approach reduced EMT in tumor cells and enhanced the antitumor immune response, primarily through CD8 T cells, as depleting CD8 cells largely abrogated the effect of treatment." (PMID 39857986, 2025). "Functionally, LIF promoted GC cell proliferation, colony formation, invasion, migration, and in vivo tumor growth." (PMID 41163398, 2025). "Together, these findings suggest that chemo/anti-LIF/anti-PD-L1 treatment modulates monocytes/macrophages, promoting a shift toward a proinflammatory, anti-tumor phenotype." (PMID 39857986, 2025). "For instance, transient TGF-β stimulus can induce LIF expression in both tumor and stromal cells via DNA hypomethylation of CpG pairs and changes in histone methylation status." (PMID 41514582, 2025). "As LIF inhibition holds promise in targeted HCC therapy, we aimed to discover an LIF inhibitor while evaluating its anti‐tumor effect and illuminating its mechanisms by targeting LIF." (PMID 40416597, 2025). "The role of LIF/LIFR signaling in the tumor microenvironment (TME) is a topic of growing interest, particularly its interactions with immune cells and transcriptional regulators." (PMID 41163398, 2025). "In vivo, C26 tumor-bearing mice showed an increase in circulating LIF that preceded and exceeded the increase in IL-6." (PMID 40869331, 2025). "Further signal pathway analysis in tumor cells revealed that the EMT pathway is the most significantly downregulated pathway following chemo/anti-LIF/anti-PD-L1 treatment." (PMID 39857986, 2025). "Previous studies have reported some natural compounds, such as stachydrine hydrochloride (SH), which exerts tumor suppressive effects in HCC by suppressing LIF expression while increasing p‐AMPK to evoke autophagy as well as cell cycle arrest." (PMID 40416597, 2025). "The results of LIF and Ki‐67 IHC staining also showed that PDX mice with high LIF expression displayed more malignant tumor proliferation than those with low LIF expression." (PMID 40416597, 2025). "Leukemia-inhibitory factor (LIF) released by the tumor promotes CAF activation and helps promote the pro-cancer response of TGF-β." (PMID 40872475, 2025). "While LIF promotes tumor proliferation, chemoresistance, and immune suppression via JAK/STAT3, MAPK/ERK, and Hippo‐YAP signaling, its context‐dependent tumor‐suppressive roles add layers of complexity." (PMID 41163398, 2025). "Having established that CVB‐D functions as a LIF inhibitor with prominent anti‐tumor characteristics, we embarked on an in‐depth exploration of its efficacy and the underlying mechanisms through which it exerts inhibitory effects on HCC in vitro." (PMID 40416597, 2025). "Emerging evidence indicates that LIF drives tumor progression by promoting epithelial–mesenchymal transition, immune evasion, and chemoresistance." (PMID 41163398, 2025). "Third, chemo/anti-LIF/anti-PD-L1 also promotes DC maturation/activation, suggesting it enhances tumor antigen presentation and ultimately triggers the activation of effector CD8 T cells." (PMID 39857986, 2025). "In K/L-driven tumor cells, LIF signaling can drive tumorigenesis by reprogramming myeloid cells (including granulocytes, monocytes and macrophages) in the TIME." (PMID 40568576, 2025). "Tumor cells overexpressing LIF amplified this TAM‐induced resistance, while LIF deficiency attenuated it." (PMID 41163398, 2025). "IL-1β regulates tumor therapeutic responses and immune activation, while the LIF-mediated secretory pathway contributes to drug resistance in tumor cells." (PMID 39893499, 2025).
tumor (continued). "Altogether, these results suggest that LIF inhibition suppresses tumor growth and metastasis by activating p38MAPK/p62‐modulated mitophagy in HCC therapy." (PMID 40416597, 2025). "further investigated the anti‐tumor potential of LIF by examining its effect on cell cycle regulation in GC." (PMID 41163398, 2025). "Tumor cell-derived SOX9 orchestrates the polarization of TAMs towards the M2 phenotype through the paracrine secretion of leukemia inhibitory factor (LIF), thereby attenuating CD8+ T cell function." (PMID 40607254, 2025). "Accordingly, we elucidated that CVB‐D induced mitophagy by triggering the LIF/p38MAPK/p62 pathway, which was mainly responsible for its anti‐tumor effect, concomitant with cell cycle arrest." (PMID 40416597, 2025). "While LIF is widely recognized for its tumor‐promoting effects, it also paradoxically influences tumor suppression and apoptosis, underscoring the complexity of its function." (PMID 41163398, 2025). "In this study, LIFR, a leukemia inhibitory factor receptor, interacts with LIF to trigger multiple signaling pathways, including those promoting tumor progression and metastasis as well as inhibiting tumor proliferation and invasion." (PMID 40108662, 2025). "Tumor‐derived LIF was identified as a critical driver of chemoresistance through TAM‐dependent mechanisms." (PMID 41163398, 2025). "Blockage of brain activation by LIF KO or Gal3 KO delayed tumor growth in the mouse allograft models of LLC, RM1, MC38, or 4T1 cells." (PMID 38467743, 2024). "Based on the current research, LIF aids in tumor growth and invasiveness by preventing differentiation and activating the JAK/STAT3 pathways." (PMID 39451257, 2024). "BMSCs contribute to the pro-inflammatory tumor microenvironment by expressing key factors such as IL-1β, TNFα, LIF, and COX2, which support MM proliferation." (PMID 39609411, 2024). "Research indicates that inhibiting circSEPT9 can induce tumor cell apoptosis and inhibit tumor growth by downregulating the LIF/STAT3 signaling pathway." (PMID 39584047, 2024). "Meanwhile, consistent with the findings with LIF KO, neural activities in the Ve-L/-R persisted in those tumor-bearing mice treated with EC330." (PMID 38467743, 2024). "LIF signaling has also been demonstrated to have extrinsic effects in the tumor microenvironment in addition to its tumor intrinsic effects." (PMID 38789520, 2024). "Further studies revealed that anti-LIF antibody 1G11 increased immune cell infiltration in tumor tissues." (PMID 39169307, 2024). "LIF/LIFR signaling plays a key role in tumor growth, progression, metastasis, stemness, and therapy resistance." (PMID 39518071, 2024). "M2d macrophages are stimulated via IL-6 and leukemia inhibitory factor (LIF); they promote angiogenesis and tumor progression via the release of vascular endothelial growth factors and dampening of the immune response." (PMID 38255280, 2024). "A LIF blockade or genetic LIFR deletion slow tumor progression and augment the efficacy of chemotherapy." (PMID 39518071, 2024). "In this work, we developed the antagonist antibody 1G11 against LIF and investigated its anti-tumor mechanism and its therapeutic efficacy in mouse models." (PMID 39169307, 2024). "Overexpression of LIF induces the proliferation of cultured human cancer cells and increases the growth of xenograft tumors formed by many human tumor cells." (PMID 39451257, 2024). "Our findings utilizing various LIFR-KO and OCa models showed that LIF is produced by OCa cells and is crucial for OCa proliferation and tumor development via LIFR in an autocrine way." (PMID 38789520, 2024). "OCa-associated mesenchymal stem cells are shown to secrete IL6 and LIF to induce tumor cell stemness." (PMID 38789520, 2024). "Therapeutically, pharmacological targeting LIF‐SE‐LIF/LIFR‐STAT3 significantly impairs tumor growth and reduces CSC subpopulations in xenograft and PDX models." (PMID 39206755, 2024).
tumor (continued). "In untreated mice, LIF levels rose to a mean level of approximately 30 pg/mL before rapidly decreasing to below 20 pg/mL as tumor volume rapidly increased." (PMID 39451257, 2024). "In conclusion, we have shown that LIF promotes the establishment of an adaptative survival niche in the tumor microenvironment, through the over-phosphorylation of STAT3 leading to FGFR4 overexpression." (PMID 37945798, 2024). "Collectively, our results highlight the potential of the LIF/LIFR antagonist antibody 1G11 as an effective tumor therapeutic strategy." (PMID 39169307, 2024). "The link between SOX9, expressed in tumor cells, and the CSF-1R, expressed by TAMs and particularly by the M2-like subset, is mediated by LIF/LIFR signaling." (PMID 39457693, 2024). "We further demonstrate that pharmacologic or genetic blockage of cancer cell-derived LIF or Gal3 signaling abolishes the brain responses and strongly inhibits tumor growth." (PMID 38467743, 2024). "Our findings, derived from the analysis of public cancer databases alongside 32 established, primary OCa cell lines, and tumor tissues reveal the existence of an autocrine loop involving LIF/LIFR." (PMID 38789520, 2024). "The combination of LIF neutralizing antibodies with the inhibition of the PD1 immune checkpoint promotes tumor regression, immunological memory, and an increase in overall survival." (PMID 38789520, 2024). "LIF/LIFR activation occurs more prominently in TNBC compared to estrogen receptor positive (ER+) BC, and high circulating LIF levels correlate with tumor recurrence and contribute to chemoresistance." (PMID 39518071, 2024). "The authors have yet to demonstrate that the myeloid cells resulting from tumor-derived IL-1 and LIF truly function as MDSCs." (PMID 37141182, 2023). "LIF signaling is shown to facilitate communication between tumor cells and fibroblasts and mediates stromal fibroblasts’ pro-invasive activation." (PMID 38139260, 2023). "The LIF/LIFR axis plays a central role in tumour growth and progression, regulating key aspects of cancer biology including cancer cell growth, proliferation, migration and chemotherapy resistance." (PMID 36998446, 2023). "Consistent with this view, an aberrant production of LIF and/or an increase in the circulating levels of LIF correlate with tumour chemoresistance in several solid cancers." (PMID 36998446, 2023). "We also show a parallel mode of cytokine communication between tumor cells and the splenic niche through leukemia inhibitory factor (LIF)." (PMID 37134077, 2023). "LIF is a member of the pro-inflammatory IL-6 family of cytokines and as such a potential contributor to tumor growth." (PMID 37296899, 2023). "Tumor-secreted IL-1 induces Leukemia inhibitory factor (LIF) expression and downstream JAK/STAT3 activation, generating inflammatory CAFs." (PMID 38124183, 2023). "LIF also facilitates the pro-tumor effects of TGF-β and is correlated with a poor clinical prognosis." (PMID 36980785, 2023). "Among the ligands of LIFR, LIF is overexpressed and has been identified playing a tumor-promoting role in various tumors, including prostate, nasopharyngeal, breast, gastric, endometrial, colorectal, melanoma, osteosarcoma, lung and pancreatic cancers." (PMID 36925915, 2023). "The LIF cytokine, which displays pleiotropic effects depending upon cell context, is secreted by tumor cells, but its precise function in the tumor context remains elusive." (PMID 38137514, 2023). "We identify tumor produced IL-1α and leukemia inhibitory factor (LIF) acting on splenic HSPCs and splenic niche cells, respectively." (PMID 37134077, 2023). "Tumor cells secrete paracrine factors such as IL-1, which activates NF-κB signaling and expression of leukemia inhibitory factor (LIF) in iCAFs." (PMID 37626931, 2023). "Blocking ATX activity changed the phenotype of the mice by decreasing the plasma concentrations of CXCL9, CXCL10, and CCl2 and the tumor concentrations of LIF, TGFβ1, TGFβ2, and prolactin." (PMID 37296899, 2023).
tumor (continued). "We also examined LIF status in endometrial carcinosarcoma using the publicly available OncoDB platform, which enables the comparison of gene expression between tumor and normal tissues using validated databases." (PMID 38139260, 2023). "Recent cancer literature has revealed that LIF is a contributor to immune evasion and facilitation of tumor growth and metastasis." (PMID 37033980, 2023). "We observed a direct correlation between LIF concentration and STAT3 activation, indicating that, in these tumor-derived cells, it is mainly LIF or a LIF-induced secreted factor that activates STAT3." (PMID 38137514, 2023). "In conclusion, these findings shed crucial light on the dynamic interplay between LIF secretion and STAT3 activation, providing valuable insights into the regulatory mechanisms underlying stemness in tumor-derived cells." (PMID 38137514, 2023). "It is possible that autocrine loops of cytokines such as LIF/LIFR in the tumor microenvironment induce multiple-cell survival and thus contribute to the low efficacy of the approved therapies." (PMID 38139260, 2023). "One the other hand, LIF–LIFR interaction also occurred between tumor cells and stromal cell types such as CAF and endothelial cells." (PMID 37360193, 2023). "LIF has immunosuppressive functions in some tumour contexts, in part by repressing CXCL9 (also part of the IPASS) and CD8+ T-cell infiltration of tumours." (PMID 37013636, 2023). "In concert with tumor-produced LIF that expands the quantity of splenic HSPC niche cells, tumor-derived IL-1α induces TNFα expression by HSPCs to alter niche function into favoring increased EMH." (PMID 37134077, 2023). "Expression of LIF was higher in TM4SF1+ tumor cells and proliferative tumor cells, particularly in advanced CRC tissues." (PMID 37360193, 2023). "We developed a functional assay based on the ability of conditioned media (CM) from tumor-derived cell lines to modulate mESC pluripotency, which is dependent on LIF." (PMID 38137514, 2023). "The presence of LIF in the serum of PyMT-B6-bearing animals and the production of LIF by tumor lines used in this study, 1956, LLC, and PyMT-B6 cells, was independently confirmed." (PMID 37134077, 2023). "Next, the investigators also demonstrated production of leukemia inhibitory factor (LIF) by tumor cells, which induced expansion of HSPC and myeloid progenitors in the spleen and promoted neutrophilia." (PMID 37141182, 2023). "Specifically, breast, ovarian, pancreatic, and nasopharyngeal cancers, have demonstrated that LIF overexpression by tumours contributes to tumor growth and metastasis as mediated by the STAT3 pathway." (PMID 37033980, 2023). "LIF has been shown to promote tumor growth and metastasis through carcinoma cell proliferation, however in our in vitro models there were limited alterations to proliferation across various cell types- 12Z, hESC, and HUVEC." (PMID 37033980, 2023). "Tumor-associated MSCs induce angiogenesis through secretion of TNFα, vascular endothelial growth factor (VEGF), interferon (INF)γ, leukemia inhibitory factor (LIF), macrophage colony-stimulating factor (M-CSF) and endothelin secretion by tumor cells." (PMID 37046676, 2023). "Preliminary analysis of a 44-member cytokine array on serum from MMTV-PyMT tumor-bearing animal compared to littermates identified LIF, an IL-6 family member, as being significantly and consistently up-regulated by the presence of tumors." (PMID 37134077, 2023). "As a potentially relevant receptacle for stemness and/or differentiation activities of the tumor secretome, we selected murine ESCs, which rely on the LIF cytokine for maintaining their undifferentiated state." (PMID 38137514, 2023). "JAM3, LIF, CD38, and SIGGIR, upregulated in our study, exert angiogenic and tumor-promoting effects and are linked to unfavorable cancer prognosis." (PMID 37762335, 2023).